GAP43 (growth associated protein 43)
Diseases named in the same sentence as GAP43 in open-access papers (continued):
Sharing a sentence is not in itself a finding about the gene and the disease.
tumor (continued). "The CRX+/EBF3+/GAP43+ tumor population (clusters 0 and 2), presenting numerous genomic alterations, appeared to be genomically homogeneous." (PMID 34552068, 2021). "According to the Expression Atlas, the hypoxia-associated molecules CALB1, DDAH1, GAP43 and GPR37, as well as the tumor markers ART3, ENOL2 and FMOD and the tumor promoter NTNG1, are typically expressed in hematopoietic stem cells." (PMID 32466393, 2020). "Growth-associated protein 43 (GAP43), which normally helps neurons grow axons, is one critical gene that tumor cells use to extend these TNTs." (PMID 32178454, 2020). "This study found that Growth Associated Protein-43 (GAP43) is essential for the development of TMs and the tumor cell network associated with GB progression, and it drives TM-dependent tumor cell invasion, proliferation, interconnection, and radioresistance." (PMID 31718063, 2019). "In tumour tissues, expression level of GAP43 was significantly higher comparing with adjacent non‐tumour tissue." (PMID 31568662, 2019). "Growth-Associated Protein 43 (GAP43) is necessary for TM formation and function, and it drives microtube-dependent tumor cell invasion, proliferation, interconnection, and radioresistance." (PMID 31846454, 2019). "Methylation analysis of the Cdh1, Cdh2, Mmp9, Mki67, Gfap, Gap43, Robo2, and Slit2 genes from tumor samples demonstrated that all of them were methylated in their promoter regions unlike those from normal tissues." (PMID 31921388, 2019). "Targeting the protein machinery in tumor TMs (i.e., Connexin43, GAP-43) by knockdown approaches induced both markedly increased survival, radio- and chemo-sensitivity, through the loss of the GBM tumor TM network." (PMID 30897774, 2019). "This is explained by the fact that GAP43 induces tumor microtube formation just as it triggers axon generation in neurons." (PMID 31058089, 2019). "In both TCGA and local cohorts of PTC, the clinicopathologic feature analysis showed that the overexpression of GAP43 was significantly related to the aggressive clinicopathologic characteristics, such as tumour size and LNM." (PMID 31568662, 2019). "In summary, GAP43 drives microtube-dependent tumor cell invasion, proliferation, interconnection, leading to resistance toward radiotherapy-induced cell death." (PMID 31058089, 2019). "Therefore, suppression of the GAP43 functional activity might inhibit both cancer progression and metastasis, and EO is an excellent candidate for the role of both analgesic and cytostatic medicinal substance applied for the treatment of tumor-associated pain syndromes." (PMID 41383576, 2025). "We also cannot exclude a paracrine contribution in vivo, as we observed several CGRP-positive, SP-positive and GAP43-positive nerve fibres around autochthonous RP tumours, which could potentially engage in paracrine communication with the tumours." (PMID 40931078, 2025). "Importantly, they additionally determined that the inhibition of growth-associated protein 43 (GAP43), which is responsible for the formation of tumor microtubes in GBM cells and in astrocytes, leads to decreased mitochondria transfer." (PMID 38786032, 2024). "Moreover, the inhibition of Gap43 disrupts the formation of intercellular connections between tumour cells mediated by TMs, indicating that Gap43 is crucial for establishing homotypical tumour cell–tumour cell connections through TMs." (PMID 38567664, 2024). "Interestingly, despite the fact that CRC tumor tissues have a reduced level of GAP43 compared with adjacent tissues, overexpression of GAP43 induces expression of ABC transporters, which are responsible for drug resistance." (PMID 37205121, 2023). "Our data from human glioblastoma cancer cell lines, as well as primary cells, showed that TNTs are rich in GAP43 and 14-3-3-γ protein and that upon chemotherapy treatment and radiation, tumor cells induce the formation of TNTs with neighboring non-tumor and tumor cells." (PMID 37476291, 2023).
tumor (continued). "Genetic or pharmacological inhibition of GAP43 or MARCKS could be employed to specifically interfere with tumor growth." (PMID 31058089, 2019). "In addition, some clinicopathological features of GAP43 in TCGA database showed that up‐regulated GAP43 is significantly connected to lymph node metastasis (P < 0.001) and tumour size (P = 0.038)." (PMID 31568662, 2019). "To determine whether GAP43 and FEZ1 are simply required for tumor growth in vivo, we transplanted Gap43 and Fez1 knock-down cells subcutaneously and quantified tumor growth." (PMID 31833833, 2019). "Hence, we collected 50 pairs of tumour samples and adjacent normal tissues to validate the expression of GAP43 by using quantitative reverse transcription‐polymerase chain reaction (qRT‐PCR)." (PMID 31568662, 2019). "Identification of EGF, RHOD, and GAP43 interaction central nodes suggests the disruption of the growth factor signaling, cytoskeletal dynamics, and neuronal differentiation, which could collectively impair tumor progression and metastasis." (PMID 41470892, 2025). "Moreover, genetic targeting of GAP-43 could suppress tumor growth after surgery by impairing formation and function of TMs and therefore could reduce tumor recurrence upon surgery by repopulation." (PMID 32244839, 2020). "Therefore, screening for potential GAP43 inhibitors could lead to novel compounds specifically targeting GAP43 in these so far incurable neoplasms." (PMID 31058089, 2019). "Interestingly, vesicular glutamate transporter 1 (VGluT1)-, P2X purinoceptor 3 (P2X3)- and growth-associated protein 43 (GAP43)-positive nerve fibres were detectable in a subset of healthy PNECs, clustered into neuroepithelial bodies (NEBs), and in small SCLC tumours." (PMID 40931078, 2025). "Stable LIN28B downregulation resulted in a significant decrease in the tumor markers SOX2, NESTIN, and SOX9 and an increase in the neural differentiation marker GAP43, consistent with the critical role of LIN28B in maintaining stemness." (PMID 38732012, 2024). "The expression levels of CDKN2A were upregulated whereas GAP43, CPT2 and NRG1 were downregulated in tumor tissues of CRC patients." (PMID 37205121, 2023). "mRNA expression of Gap-43 was 8.3- and 5.4-fold higher in iWAT of LLC and C26 tumor-bearing mice compared with control animals and C26nc tumor-bearing mice, respectively." (PMID 35210363, 2022). "Thus, when comparing the GAP43 gene expression patterns in a series of CRC cell lines, immortalized colorectal epithelial cell line, tumor cells and normal cells, we deduced that the accumulation of aberrant methylation of GAP43 gene might drive the initiation of CRC." (PMID 33402155, 2021). "Analysis of the protein 14-3-3γ and GAP43, both present in TNT and tumor microtubes, were mainly concentrated at the interface between the tumor and the healthy brain tissue." (PMID 34267246, 2021). "Results showed that histological type (P < 0.001), tumour size (P = 0.038) and LNM (P < 0.001) were significantly related to high GAP43 expression." (PMID 31568662, 2019). "The expression of a specific module—whose regulators were GAP43 and WWTR1 genes—had been reported to correlate with the necrotic process and with the presence of blurry edge necrotic portion of the tumor." (PMID 31795520, 2019). "In distinct human tumors, mainly oncogenic properties are described for GAP43 and MARCKS, whereas for BASP1 a general tumor suppressive function has been reported." (PMID 31058089, 2019). "Whereas GAP43 and MARCKS are oncogenic, tumor suppressive functions have been ascribed to BASP1 and in part to MARCKS depending on the cell type." (PMID 31058089, 2019). "Conversely, larger tumours mostly lacked intralesional nerve fibres and, when present, GAP43- and synaptophysin (SYP)-positive fibres were observed at the tumour border." (PMID 40931078, 2025).
tumor (continued). "The anti-GAP43 antibody had a good specificity with almost no positive staining in tumor cells or other stromal cells of the TME as compared to other antibodies for established marker proteins." (PMID 38920662, 2024). "The co-expression of CRX/EBF3/GAP43 (early photoreceptor/cone marker and neuronal/ganglion cell markers) was unique to tumor cells as it was absent or very rare during normal retinal development." (PMID 34552068, 2021). "Interestingly, protein 14-3-3γ and GAP43 were mainly localized in the cell body and the TNT-like processes at the interface between the tumor and the healthy brain area (green staining)." (PMID 34267246, 2021). "Besides their functions in neurons, GAP43, MARCKS, and BASP1 are also expressed in non-neuronal cells, and display intrinsic oncogenic or tumor suppressive functions." (PMID 31058089, 2019).
cancer (16 papers, 2013 to 2025). A tumor composed of atypical neoplastic, often pleomorphic cells that invade other tissues. "This suggests that GAP43 is likely to be associated with drug resistance to cancer chemotherapy drugs." (PMID 33402155, 2021). "The best polygenetic model included DIRC3_rs6759952, GAP43_rs13059137, NRG1_rs7834206, PROM1_rs72616195, LRP1B_rs1369535, and LOC100507065_rs11175834, tumorigenesis and cancer cell differentiation-related genes." (PMID 33805984, 2021). "GAP43 and BASP1 have previously showed significant associations with tau concentration, together with for example the cancer-associated protein LY6H, and PEBP1 which is believed to have implications for AD." (PMID 33653397, 2021). "Quantification of GFPpositive cancer cells in the liver by flow cytometry documented a significant reduction in metastatic seeding by SCLC cells with Gap43 or Fez1 knocked-down." (PMID 31833833, 2019). "In osteolytic bone metastasis neurite-like structures are found intra-tumoral, therefore, Gap43 positive cells likely re-present an osteolytic cancer cell niche component." (PMID 29988965, 2018). "Of interest, this selection contained genes present in 5 out of 10 regions of homozygous loss found in our study and several genes known to be implicated in cancer and neuronal differentiation (such as NF1 and GAP43)." (PMID 23308108, 2013). "Numerous studies have investigated the role of GAP43 in promoting or inhibiting cancer development." (PMID 35884600, 2022). "Notably, the proteins which had the biggest fold change in differentiated hVM1 clone 32 cells, GAP43, DCLK1, and EEF1A2, are implicated in several cancers." (PMID 35126116, 2021). "In addition, a recent study demonstrated that GAP43 affects cancer development." (PMID 36684596, 2022). "Therefore, GAP43 might affect the chemotherapy drug resistance in cancer patients through ABC transporter-mediated signaling pathway." (PMID 33402155, 2021). "Cells in cluster 5 resembled those in cluster 7 of DNs, and included cells with aberrant neuronal identity that expressed neuronal genes (GAP43, NEFM, DCX, HES6) and cancer-related proliferative genes (CRABP1, MYC, SFRP1)." (PMID 33771987, 2021). "However, the role of GAP43 in human cancers, especially CRC, has not been explored to date." (PMID 33402155, 2021).
neurodegenerative disease (14 papers, 2011 to 2025). A disorder of the central nervous system characterized by gradual and progressive loss of neural tissue and neurologic function. "Among them, synaptosome-associated protein 25 (SNAP25), growth-associated protein 43 (GAP43), neurogranin, and synaptotagmin 1 are widely investigated in neurodegenerative diseases." (PMID 38528511, 2024). "Another aspect to consider that could explain why Cd is counted among the etiopathogenetic factors of degenerative diseases is the Cd-dependent downregulation of growth associated protein-43 (GAP-43) and βIII-tubulin in differentiated SH-SY5Y cell line." (PMID 32516892, 2020). "Further exploration of these areas using human-derived neuronal lines will be crucial to corroborate the effects of GAP-43 S86 and T172 phosphomimetic mutants and facilitate the development of GAP-43-targeting therapies for neurodegenerative diseases." (PMID 40259946, 2025). "Regulation of GAP-43 has been explored as a therapeutic strategy for neurodegenerative diseases." (PMID 40259946, 2025). "By discussing GAP-43 and BASP1 in the context of neurodegenerative diseases, we also explore the therapeutic potential of modulating their activities to compensate for neuron loss in neurodegenerative diseases." (PMID 33015061, 2020). "The involvement of disordered proteins in neurodegenerative diseases questions whether GAP-43 and BASP1 also phase separate in this context, whether this process turns aberrant, and what the functional consequences are." (PMID 33015061, 2020). "Growth-associated protein 43 (GAP43) and synaptophysin (Syn) are synaptic proteins that are associated with axonal sprouting and synaptogenesis in various neurodegenerative diseases and may accumulate in regenerating neurons and axons." (PMID 28302146, 2017). "Finding effective pharmacological treatments for modulating the expression or the activity of GAP-43 may contribute to sustain axonal structures, preventing axonal dying back in neurodegenerative diseases." (PMID 21695168, 2011). "If nothing else, the exploration of GAP-43 function and upstream and downstream regulators has stimulated the search for targeted therapeutics directed to facilitate CNS regeneration after axonal injury and possibly, developmental disorders, memory dysfunction and neurodegenerative diseases." (PMID 28912688, 2017). "GAP-43, β3-tubulin, p-Akt, and p-CRMP2 are involved in axon degeneration in neurodegenerative diseases." (PMID 39507404, 2024). "Further exploration of these areas will facilitate the development of GAP-43- and BASP1-targeting therapies for neurodegenerative diseases." (PMID 33015061, 2020). "Interestingly, examinations of GAP-43 and BASP1 in neurodegenerative diseases reveal alterations in their expression and phosphorylation profiles." (PMID 33015061, 2020).
infection (3 papers, 2015 to 2024). The state of being infected such as from the introduction of a foreign agent such as serum, vaccine, antigenic substance or organism. "Significant increases in the expression of GAP-43 were induced in the spinal cord of Lenti-shSOCS3-infected animals, as compared to those with Lenti-pGipz infection." (PMID 26384335, 2015). "Notably, SCI-induced GAP-43 expression was even more significant and dramatic with Lenti-shSOCS3 infection, as compared to the increases induced by Lenti-pGipz infection in the spinal cord both rostral (4-fold increase) and caudal (2.2-fold increase) to the lesion epicenter." (PMID 26384335, 2015).
cardiac diseases (2 papers, 2019 to 2025). "Our results suggest that GAP-43 has a key role in the regulation of Ca2+ and ROS homeostasis, alterations to which could trigger heart disease." (PMID 40227418, 2025). "Therefore, deep exploration on the functions of HCN channels in GAP-43 expression and neurite outgrowth may contribute to unlocking the neurologic mechanisms of sympathetic nerve sprouting in cardiac diseases such as MI." (PMID 31616252, 2019).
cardiovascular disease (2 papers, 2018 to 2022). "CMS causes cardiac and T1–5 spinal cord electrophysiological abnormalities as well as increased cardiac expression of 5-HT and GAP-43, indicating that CMS could potentially increase the risk of cardiovascular disease." (PMID 29707580, 2018). "In summary, the hub genes related with M2 macrophages that we searched include CCL22, C1orf105, GAP43, and PTPN21, all of which imply a relationship with cardiovascular disease, which is consistent with our findings." (PMID 36222281, 2022).
nervous system diseases (2 papers, 2023 to 2025). "The abnormal expression of gap43 is associated with various nervous system diseases." (PMID 40265358, 2025).
neurodevelopmental disorder (2 papers, 2023 to 2025). A behavioral and cognitive disorder with onset during the developmental period that involves impaired or aberrant development of intellectual, motor, or social functions. "While we detail here the genetic and epigenetic mechanisms of Pvt1 ME and its functional consequence, there are several aME genes from our list that are associated with neurodevelopmental disorders, such as Grik3, Mettl5, Gap43, and Tubb3." (PMID 41223055, 2025).
peripheral neuropathies (2 papers, 2017 to 2022). "In humans, GAP-43 expression particularly in cutaneous axons has repeatedly been examined in the context of peripheral neuropathies and links with regenerative capacity were drawn." (PMID 36383568, 2022). "Third, this is the first study examining GAP-43 expression in the glabrous finger skin in patients with peripheral neuropathy." (PMID 36383568, 2022). "In humans, expression of GAP-43 has predominantly been examined in skin biopsies from patients with peripheral neuropathies; with several studies showing a reduction in GAP-43 immunoreactive cutaneous nerve fibres." (PMID 36383568, 2022). "Previous work suggests that GAP-43 is changed particularly in patients with shorter disease duration; mRNA in the proximal thigh is only elevated in patients with peripheral neuropathies and disease duration <3 years." (PMID 36383568, 2022). "Several studies have reported a reduction in GAP-43 immunoreactive cutaneous nerve fibres in patients with peripheral neuropathies." (PMID 36383568, 2022).
myopathies (1 paper, 2013). "In particular, its expression was revealed in muscles from patients affected by various myopathies, indicating that GAP43 can no-longer considered only as a neuron-specific molecule." (PMID 23308181, 2013).
psychiatric disorder (1 paper, 2024). A disorder characterized by behavioral and/or psychological abnormalities, often accompanied by physical symptoms. "Here, we found that mice lacking the protein GAP43 selectively in telencephalic glutamatergic neurons show a robust novelty-induced hyperactive phenotype, a behavioral deficit often associated to psychiatric diseases." (PMID 39168654, 2024). "Our findings thus unveil an important role of GAP43 in corticostriatal function and provide a new animal model with a delimited neuronal-circuit alteration for studying novelty-induced hyperactivity in psychiatric disorders." (PMID 39168654, 2024). "Taken together, these findings show an unprecedented regulatory role of GAP43 in the corticostriatal circuitry and provide a new mouse model with a delimited neuronal-circuit alteration for studying novelty-induced hyperactivity, a phenotypic shortfall that occurs in diverse psychiatric diseases." (PMID 39168654, 2024).
GAP43 also shares sentences with these, for which no sentence is quoted: cerebral infarction (3 papers); amyotrophic lateral sclerosis (2); acute myeloid leukaemia (1); Ataxia (1); Atrophy (1); attention deficit-hyperactivity disorder (1); autoimmune thyroid disease (1); brain disorder (1); carpal tunnel syndrome (1); cerebral embolism (1); cerebral palsy (1); chronic hepatitis B (1); CNS lymphoma (1); colon adenocarcinoma (1); complex regional pain syndrome (1); coronary artery disease (1); cortical atrophy (1); Creutzfeldt-Jakob Diseases (1); delirium (1); diabetic polyneuropathy (1); encephalopathies (1); experimental autoimmune encephalomyelitis (1); facial paralysis (1); fibromyalgia (1); Gliosis (1); Huntington disease (1); hypoxic-ischemic encephalopathy (1); Lewis lung carcinoma (1); Lyme Neuroborreliosis (1); malnutrition (1).
A further 18 diseases each share a sentence with GAP43 in 1 paper.